CERS2 (ceramide synthase 2)
Diseases named in the same sentence as CERS2 in open-access papers (continued):
Sharing a sentence is not in itself a finding about the gene and the disease.
colitis (5 papers, 2017 to 2024). Inflammation of the colon. "In their study, CerS2-deficient mice were much more sensitive against DSS-induced colitis and developed more colon tumours after AOM/DSS treatment." (PMID 38635059, 2024). "Compared to WT controls, CerS2 null mice displayed aggravated colitis as manifested by greater bodyweight loss and worse survival rates." (PMID 28699686, 2017). "In conclusion, deficiency of CerS2 influences intestinal barrier function and the severity of experimental colitis and may represent a potential mechanism for inflammatory bowel disease pathogenesis." (PMID 28699686, 2017). "Together, these findings suggest that CerS2 deficiency exacerbates experimental colitis in mice." (PMID 28699686, 2017). "The impact of CerS2 on colon carcinogenesis was studied by two groups applying the DSS- and AOM/DSS-induced colitis colon cancer model to CerS2 knockout mice." (PMID 38635059, 2024). "CerS2 null mice exhibited severe colitis upon DSS treatment, along with increased intestinal permeability, higher myosin light chain 2 (MLC2) phosphorylation and diminished levels of junctional adhesion molecule‐A (JAM‐A) in the colon." (PMID 28699686, 2017). "Similar to the data from BM chimeric mice, CerS2 null recipients with mixed BM also showed severe colitis." (PMID 28699686, 2017). "In this study, we used CerS2 null mouse to investigate the role of very‐long chain ceramides in experimental colitis." (PMID 28699686, 2017). "In addition, in CerS2-deficient mice, DSS-induced colitis and CAC are enhanced in comparison to wt mice." (PMID 32630271, 2020). "In CerS2 knockout mice, we could demonstrate that these mice develop more severe colitis after dextran sodium salt (DSS) treatment than CerS2 WT mice." (PMID 29540995, 2018). "CerS2 null mice displayed increased intestinal permeability and exacerbated colitis induced by DSS." (PMID 28699686, 2017). "As DSS‐induced colitis is driven by innate immune cells 29, 30, we generated BM chimeras in which WT or CerS2 null mice received either CerS2 deficient or WT BM to examine whether any cells of haematopoietic origin are involved in the development of colitis in CerS2 null mice." (PMID 28699686, 2017). "In CerS2-knockout (ko) mice, depletion of very-long chain ceramides is connected with disruption of the membrane integrity by downregulation of tight junction protein occludin and zonula occludens-1 (ZO-1), leading to enhanced severity of AOM/DSS-induced colitis in these mice." (PMID 31277430, 2019).
colon cancer (5 papers, 2017 to 2024). "Overexpression of CerS2 and co-expression with CerS6 or CerS4 in colon cancer cells have been shown to promote proliferation, whereas overexpression of CerS4 and CerS6 had rather anti-proliferative effects." (PMID 38635059, 2024). "In summary, an increase of CerS2, resulting in enhanced production of very-long-chain ceramides and GlcCer, has been detected in human colon cancer tissue, especially in late-stage tumours." (PMID 38635059, 2024). "Accumulating evidence suggests that the overexpression of Cers2 leads to increased cell proliferation in colon cancer cell lines, while high Cers5 expression has been found in colorectal cancer tissue and is associated with poorer patient outcomes." (PMID 37298127, 2023). "Consistent with our results, overexpressing mammalian Cers2 in HT29 colon cancer cells caused a modest but significant reduction in transcription of a reporter gene regulated by an acid ceramidase promoter, suggesting that Cers2 might have additional pathway-relevant targets." (PMID 28956531, 2017). "In human colon cancer tissue, CerS2 expression increases with tumour stage." (PMID 38635059, 2024).
diabetes (5 papers, 2014 to 2024). "Ceramide synthase is known to be enhanced in LPS-mediated septic shock in Cers2-deficient mice, and inhibition of ceramide synthesis prevented diabetes, steatosis, and cardiovascular disease in rodents." (PMID 38727856, 2024). "Though it is unclear if CERS2 function influences albuminuria, it was shown that the rs267734 variant of CERS2 is associated with increased albuminuria in patients with diabetes." (PMID 35457062, 2022). "In conclusion, we found that rs267734 in CERS2 is associated with rate of increase in albuminuria among patients with diabetes and elevated risk of cardiovascular disease." (PMID 25238615, 2014). "In conclusion, we found that a SNP in the CERS2 gene that was previously found to be associated with eGFR was also associated with increase in albuminuria among patients with diabetes and elevated cardiovascular risk." (PMID 25238615, 2014).
Glucose intolerance (5 papers, 2015 to 2022). Glucose intolerance (GI) can be defined as dysglycemia that comprises both prediabetes and diabetes. "It was shown, that genetically CerS2-deficient mice displayed glucose intolerance even with physiological insulin secretion from the β-cell of the islets of Langerhans." (PMID 31496996, 2019). "This is evident as targeting CerS6 to reduce C16:0 ceramides, resulted in the prevention of diet-induced obesity and glucose intolerance, whilst the ablation of CerS2 reduced C22:0 and C24:0 ceramides, increased C16:0 ceramides and contributed to spontaneous hepatocellular carcinoma development." (PMID 34385976, 2021). "Conversely, Cer (d18:1/24:0), preferentially synthesized by ceramide synthase 2, is suggested to protect mice from HFD-induced obesity and glucose intolerance." (PMID 36313074, 2022). "Previous studies suggest CerS2-derived C22:0 and C24:0 ceramides may not be deleterious in liver, as knockdown of CerS2 led to glucose intolerance, impaired insulin signaling in the liver and the development of hepatic tumors in mice." (PMID 34385976, 2021).
Alzheimer disease (4 papers, 2019 to 2023). A progressive, neurodegenerative disease characterized by loss of function and death of nerve cells in several areas of the brain leading to loss of cognitive function such as memory and language. "CerS2 is also linked to the chronic neurodegenerative Alzheimer`s disease." (PMID 37760612, 2023). "In addition, CerS2 and its metabolites are associated with Alzheimer’s disease (AD) and CerS2 activity is reduced in early AD stages, leading to the demyelination observed in the disease." (PMID 36983060, 2023). "In an Alzheimer’s disease model, there was increased expression of CerS2 in brain tissue, which led to apoptosis in glial cells." (PMID 37760612, 2023). "Decreased CERS2 protein levels were also reported for the hypomyelination pathology in Niemann–Pick type C disease, and, interestingly, they were observed to precede tau pathology at a preclinical stage of Alzheimer’s disease." (PMID 31766565, 2019).
colorectal cancer (4 papers, 2017 to 2023). A primary or metastatic malignant neoplasm that affects the colon or rectum. "First, significant differences in gene expression between normal tissue and colorectal cancer tissue were observed for ASAH1, ACER3, CERS2, and CERS6." (PMID 37758931, 2023).
Obesity (4 papers, 2019 to 2023). Accumulation of substantial excess body fat. "Homozygous CerS2 knockout mice are highly susceptible to maladaptive metabolic disorders when fed an obesity-inducing diet." (PMID 37298446, 2023). "In addition, a recent report proposes an obesity-independent CERS2-dependent lipid signature of imbalanced very long chain:long chain ceramides as contributing to β-cell failure through impaired proinsulin processing." (PMID 37124760, 2023). "Low-dose bortezomib treatment reduced TG accumulation on the chow diet group and prevented HFD-induced obesity and fatty liver development in mice by enhancing CerS2 expression, which plays a key role in regulating ER stress and its downstream targets, SREBP-1 cleavage, and lipogenesis." (PMID 31676768, 2019).
asthma (3 papers, 2013 to 2021). "The pathogenic role of the de novo synthetic pathway has been suggested from the GWAS studies showing that ORMDL and CerS2 were significantly associated with the risk of asthma." (PMID 33031402, 2020). "We noted that CerS2 SNPs may be nominally associated with asthma in a GWAS study." (PMID 23690971, 2013). "Finally, CerS2 deficiency alone was associated with increased airways resistance, which in light of recent genomic studies of asthma could provide useful functional significance of the de novo sphingolipid pathway in this common disease." (PMID 23690971, 2013). "Given the pivotal role that Th2 cells and cytokines play in asthma pathophysiology, the severely diminished Th2 responses observed in CerS2 null CD4+ T cells are likely to contribute to the decreased severity of asthma patients." (PMID 33800208, 2021). "The current study showed that CerS2 deficiency caused reduced Th2 response and alleviated OVA-induced asthma, and suggests an important role of CerS2 and its products in asthma pathogenesis." (PMID 33800208, 2021). "Finally, CerS2 and very-long acyl chain SLs may in the future be used as therapeutic targets for the treatments of asthma and Th2-related diseases." (PMID 33800208, 2021). "CerS2 and very-long chain SLs may be therapeutic targets for Th2-related diseases such as asthma." (PMID 33800208, 2021). "Therefore, mild asthma symptoms in CerS2 null mice may suggest a pathological role of very-long chain SLs in asthma." (PMID 33800208, 2021). "Decreased Th2 and increased Th17 response with higher TCR signal strength was observed in CerS2 null CD4+ T cells upon TCR stimulation and the severity of ovalbumin (OVA)-induced asthma was decreased in CerS2 null mice, implicating a pathological role of very-long-acyl chain SLs in asthma." (PMID 33800208, 2021).
COVID-19 (3 papers, 2021 to 2023). A disease caused by infection with severe acute respiratory syndrome coronavirus 2. "The ratio of SK1 to CERS2 expression was increased in COVID-19+ and COVID-convalescent samples compared to control autopsies, with a significant increase in central lung sections of the COVID-19+ autopsy." (PMID 37868972, 2023). "The differential CERS2 expression, with an enhanced signal in type II pneumocytes in COVID-19 autopsy, is potentially due to apoptotic process initiated by viral entry and infection through ACE2 or other viral receptors in the epithelium." (PMID 37868972, 2023). "The expression of SK1 and CERS2 was assessed in control, COVID-19+, and convalescent samples using immunohistochemistry." (PMID 37868972, 2023). "Quantitation of expression of SK1 and CERS2 by QuPath analyses showed significant increase in % positive cells expressing SK1 in COVID-19+ autopsies and convalescent samples compared to control autopsies." (PMID 37868972, 2023). "SARS-CoV-2 infection upregulates SK1 and increases the ratio of SK1 to CERS2 expression in lung tissues of COVID-19 autopsies and COVID-19 convalescents." (PMID 37868972, 2023). "As SK1 expression and SK1/CERS2 ratios were increased in COVID-19+ autopsies, we then evaluated if lipid signaling through the sphingolipid receptors would be enhanced in these autopsies." (PMID 37868972, 2023). "Since Cer(d18:1/16:0) and Cer(d18:1/24:1) are the predominant subclasses seen in the plasma samples of the COVID-19-infected group, focusing on modulation of CerS2 and CerS6 seems to be the logical therapeutic approach." (PMID 34675292, 2021). "CERS2 staining was prominent in activated type II pneumocytes in COVID-19+ autopsies." (PMID 37868972, 2023). "Alterations in SK1 and CERS2 expression may correlate with the pathogenesis of lung injury in COVID-19 affected individuals." (PMID 37868972, 2023). "Furthermore, the expression levels of other enzymes associated with this pathway, such as ceramide synthase 2 (CERS2) and ceramide synthase 4 (CERS4), as well as the ceramide transfer protein (CERT1), were increased in severe COVID-19 patients." (PMID 37566018, 2023). "Alterations in SK1 and CERS2 expression may contribute to the inflammation and tissue damage during COVID-19." (PMID 37868972, 2023). "Notably, in severe forms of COVID-19, ceramide synthases (CERS2, CERS4, and CERT1) responsible for the synthesis of Cer from Sph were upregulated." (PMID 37566018, 2023).
glioblastoma (3 papers, 2019 to 2023). The most malignant astrocytic tumor (WHO grade IV). "For instance, in glioblastoma tumor cells with high expression of BCL2 like 13 (BCL2L13), CERS2 activity is blocked, resulting in the prevention of apoptosis in response to both conventional and targeted therapies." (PMID 37958652, 2023).
hepatopathy (3 papers, 2015 to 2022). "In addition to the marked hepatopathy, the lack of CerS1 and CerS2 is linked with cerebellar ataxia and multiple structural changes in the peripheral and central nervous systems, respectively." (PMID 36139213, 2022). "Since sphingosine has been long known to promote apoptosis and autophagy and the occurrence of a severe hepatopathy in CerS2-knockout mice has been shown to correlate significantly with elevated sphinganine levels, both sphingosine and sphinganine may play a pivotal role in HCV-induced hepatopathy." (PMID 27304952, 2016).
Ataxia (2 papers, 2022 to 2024). Ataxia refers to impaired coordination of voluntary muscle movement. "For example, pathogenic variants in the ceramide synthase gene CERS2 cause epilepsy and ataxia, and mutations in genes involved in sphingolipid metabolism such as B4GALNT1, GBA2, and even FA2H, cause different forms of spasticity and ataxia, such as SPG26, SPG46, and SPG35, respectively." (PMID 38911600, 2024).
breast tumor (2 papers, 2019 to 2021). "These all suggest that CerS-2 may be an important influential factor of anti-breast tumor therapeutic efficacy." (PMID 30988071, 2019).
cardiomyopathy (2 papers, 2025). A disease of the heart muscle or myocardium proper. "In humans, we showed that elevated cardiac expression of CERS2 was associated with increased expression of genes in signaling pathways linked to cardiac arrhythmia and cardiomyopathy." (PMID 40725105, 2025). "Intriguingly, although these cells have not been treated with any external compounds aside from the siRNA, it appears the HCMs with silenced CERS2 are developing an unhealthy cardiomyocyte phenotype, supported by a similar upregulation of pathways altered in human cardiomyopathy." (PMID 41002968, 2025). "Following CERS2 KD and extensive washing to remove dead cells, increases in ECM organization and cardiomyopathy pathways were observed as well as decreases in pathways involved in the cell cycle, while we observed opposing changes following CERS5/6 KD despite the cell death observed with CERS2 KD." (PMID 41002968, 2025).
epilepsy (2 papers, 2015 to 2024). A brain disorder characterized by episodes of abnormally increased neuronal discharge resulting in transient episodes of sensory or motor neurological dysfunction, or psychic dysfunction. "The ceramide synthase 2 (CerS2) catalyzes synthesis of long-chain (22:0, 24:0, 24:1) Cer, and reduction in these ceramides is associated with neurodegenerative disorders including epilepsy." (PMID 26260413, 2015).
experimental autoimmune encephalomyelitis (2 papers, 2019 to 2023). An autoimmune demyelinating disease of the central nervous system that is produced experimentally in animals by the injection of homogenized brain or spinal cord in Freund's adjuvant. "In experimental autoimmune encephalomyelitis (EAE), an animal model of multiple sclerosis (MS), the ablation of CerS2 suppresses EAE-pathology by reducing neutrophil migration into the central nervous system." (PMID 30679689, 2019).
glioma (2 papers, 2022 to 2024). A benign or malignant brain and spinal cord tumor that arises from glial cells (astrocytes, oligodendrocytes, ependymal cells). "Relative quantitation of GSLs across multiple structural levels provides evidence of dysregulated gene and protein expressions of FA2H and CerS2 in human glioma tissue." (PMID 38965283, 2024). "FA2H which is responsible for adding an OH group at the C2 position on fatty acids and CerS2 which prefers to assemble C24-CoA to the long chain base are both down-regulated at transcription and protein levels in glioma tissue." (PMID 38965283, 2024). "Indeed, we found that both the transcription and protein levels of CerS2 were significantly lower in glioma tissues as compared to normal control." (PMID 38965283, 2024).
Hepatic steatosis (2 papers, 2018 to 2025). Steatosis is a term used to denote lipid accumulation within hepatocytes. "In addition, one study showed that hepatic CerS2 haploinsufficiency increased susceptibility of mice to diet-induced hepatic steatosis, while clozapine increased hepatic CerS2 protein expression in the present study." (PMID 29720183, 2018). "A study found that hepatocyte-specific knockdown of CERS2 inhibited the p38 MAPK and ERK1/ERK2 signaling pathways in mouse liver, thereby protecting mice from high-fat diet-induced hepatic steatosis and IR." (PMID 40143173, 2025).
Progressive myoclonic epilepsy (2 papers, 2021 to 2023). "Reducing Cer level in mice via the deletion of ceramide synthase 2 (CERS2) leads to the development of progressive myoclonic epilepsy." (PMID 33776806, 2021). "In progressive myoclonic epilepsy (PME) patients, heterozygous deletions of CerS2 in fibroblasts have been observed, which suggests that a reduced CerS2 level led to PME development." (PMID 37760612, 2023).
sarcopenia (2 papers, 2024). Progressive decline in muscle mass due to aging which results in decreased functional capacity of muscles. "Increased plasma SM (16:0) and CER (24:1) levels in men with sarcopenia reflected increased CER species with fatty acid acyl chain length preferences toward long (C16:0) and very‐long chains (C24:0 and C24:1), which CERS6 and CERS2, respectively, produce." (PMID 39229927, 2024).
steatosis (2 papers, 2019 to 2024). Increased lipid within the cytoplasm of cells. "However, the present study demonstrates the relationship between CerS2 haploinsufficiency and ER stress that is linked to steatosis." (PMID 31676768, 2019). "However, the present study, for the first time, demonstrated that the relationship between CerS2 haploinsufficiency and ER stress is linked to steatosis." (PMID 31676768, 2019). "However, low-dose bortezomib treatment alleviated diet-induced steatosis and ER stress with a concomitant CerS2 increase." (PMID 31676768, 2019).
ulcerative colitis (2 papers, 2017 to 2019). An inflammatory bowel disease involving the mucosal surface of the large intestine and rectum. "Also, in the dextran sodium salt (DSS) evoked model of ulcerative colitis, an increase in very long chain ceramides in CerS2 null mice was shown, accompanied by an increase in CerS3 mRNA expression." (PMID 30679689, 2019).
Acute hepatitis (1 paper, 2017). Acute hepatic injury resulting from inflammation typically accompanied by increased serum alanine transaminase activity. "To determine the role of CerS2 in host defense against pathogens, we infected CerS2-null mice with a hepatotropic strain of LCMV, which activates pathways of both innate and adaptive immunity and causes acute hepatitis in mice." (PMID 29163475, 2017).
allergic asthma (1 paper, 2024). A asthma with a basis in a pathological type I hypersensitivity reaction. "Importantly, a previous study reported that mice deficient in CerS2 exhibited reduced sensitivity to ovalbumin-induced allergic asthma, accompanied by impaired Th2 responses." (PMID 38783005, 2024).